MTOR (mechanistic target of rapamycin kinase)
Diseases named in the same sentence as MTOR in open-access papers (continued):
Sharing a sentence is not in itself a finding about the gene and the disease.
prostate carcinoma (continued). "In this hospital-based case-control study of 413 prostate cancer (PCa) cases and 807 cancer-free controls, we investigated the role of functional single nucleotide polymorphisms (SNPs) of pivotal genes in the PI3K/AKT/mTOR pathway." (PMID 28977864, 2017). "Rapamycin in combination with other compound or inhibitors had enhanced efficacy against prostate cancer or led to decreased cell proliferation, and Giovanni Luca Gravina work also suggested that PI3K/Akt/mTOR inhibitors can be used in hormone-insensitive prostate cancer models." (PMID 28186966, 2017). "Notably, salinomycin decreased phosphorylated of AKT and phosphorylated mammalian target of rapamycin (mTOR) in prostate cancer cells." (PMID 28524116, 2017). "Recent studies have suggested that mTOR is important in the initiation and progression of prostate cancer, where it participates in forming precursor lesions such as high grade prostatic intraepithelial neoplasia, and proliferative inflammatory atrophy of the prostate." (PMID 29228561, 2017). "In addition, mTOR inhibitors such as everolimus have been shown to result in expansion of Tregs in patients with metastatic renal cell carcinoma or prostate cancer." (PMID 29070044, 2017). "This is the first evidence of mTOR-mediated regulation of HIF-1α in prostate cancer." (PMID 27821815, 2016). "Phase I/II clinical trials have shown limited efficacy of mTOR inhibitors in prostate cancer." (PMID 27096957, 2016). "Moreover, it is well documented that inhibition of both MEK/ERK and mTOR substantially enhanced their antitumor effects on prostate cancer both in vitro and in vivo." (PMID 27990160, 2016). "Furthermore, rottlerin inhibited PI3K (phosphoinositide 3-kinase)/Akt/mTOR (mammalian target of rapamycin) pathway, leading to autophagy and apoptosis in pancreatic cancer stem cells and prostate cancer cells." (PMID 27626499, 2016). "Prostate cancer patients with a high-risk of relapse have low-mTOR expressing tumors with an inactive mTOR pathway, and are consequently unlikely to benefit from mTOR inhibitor therapies." (PMID 27096957, 2016). "Furthermore, by accurately identifying translationally responsive genes and filtering out distracting false-positives, Xtail provides novel biological insights into the molecular and cellular responses to mTOR signalling perturbation in prostate cancer cells." (PMID 27041671, 2016). "Therefore, the mammalian target of rapamycin (mTOR) is frequently hyper-activated in prostate cancer." (PMID 27694690, 2016). "Since tumors from poor-outcome patients have low levels of mTOR-S2448 phosphorylation, this may explain why mTOR inhibitors proved unsuccessful in prostate cancer trials." (PMID 27096957, 2016). "However, in prostate cancer, mTOR inhibitors have demonstrated limited clinical efficacy in the castration resistant and neoadjuvant setting." (PMID 27096957, 2016). "A systemic review found that metformin use reduced the risk of prostate cancer among men with diabetes perhaps by regulating adenosine monophosphate-activated protein kinase (AMPK) pathways and mammalian target of rapamycin (mTOR)." (PMID 27547763, 2016). "Treatment with NVP-BEZ235-a PI3K/mTOR dual inhibitor–was able to sensitize human castration resistant prostate cancer cell lines C4-2 and C4-2AT6 resistant to docetaxel, indicating that mTOR inhibition can even overcome chemoresistance in castration resistant prostate cancer." (PMID 27491285, 2016). "Since mTOR inhibitors particularly target tumors with an activated mTOR pathway, linking mTOR activity with outcome could potentially explain the poor performance of mTOR inhibitors in the treatment of prostate cancer." (PMID 27096957, 2016). "As mTOR is one of the main regulators of autophagy we wondered whether capsaicin induced autophagy in prostate cancer cells." (PMID 26625315, 2016).
prostate carcinoma (continued). "One potential candidate is AKT/mammalian target of rapamycin (mTOR) signaling pathway because CXCL16 has been reported to promotes prostate cancer progression by activating the AKT/mTOR signaling pathway, which is abolished by rapamycin, a mTOR inhibitor and an anti-aging and anti-cancer drug." (PMID 27191747, 2016). "Importantly, the increase in CSCs was also inhibited both in vitro and in vivo, when the mTOR signaling pathway in prostate cancer was blocked." (PMID 27172799, 2016). "In human prostate cancer cell line PC-3, mTOR signaling pathway is an upstream activator of HIF-1." (PMID 27821815, 2016). "Previous work has also implicated p110β as a positive regulator of AR transactivation in prostate cancer cell lines and PI3K/mTOR signalling has been shown to either positively or negatively modulate AR transactivation both in prostate cancer cell lines and genetic mouse models of prostate cancer." (PMID 26132308, 2015). "Furthermore, we performed immunohistochemistry analysis on human primary prostate cancer tissue sections derived from patients to investigate the correlation of SR-BI with clinicopathological parameters and the mTOR target pS6." (PMID 26251134, 2015). "This miRNA is involved in 45 KEGG pathways according to DIANA-mirPath predictions, the most significant being prostate cancer (6.436856e-14), endometrial cancer (4.517902e-10), mTOR signalling pathway (1.336018e-07), and PI3K-Akt signalling pathway (2.347282e-07)." (PMID 26555194, 2015). "Finally, we provide preclinical evidence for the development of targeted treatment strategies based on the use of multikinase inhibitors, such as sorafenib, in combination with mTOR inhibitors for the treatment of advanced prostate cancer." (PMID 25953027, 2015). "Currently, several small-molecule inhibitors targeting different proteins of the PI3K/AKT/mTOR pathway, especially a class of dual PI3K/mTOR inhibitors, which bind to and inactivate both PI3K and mTOR, have shown potent anticancer activity in prostate cancer in pre-clinical and clinic trials." (PMID 26506516, 2015). "In addition, MEK inhibitor treatment of hormone-refractory human prostate cancer cells induces mTOR phosphorylation." (PMID 26121028, 2015). "In this study, the role of AMPK/mTOR signaling pathway and the interplay with Chk2 in apoptosis have been identified in nitroxoline-mediated anticancer effect in both hormone-sensitive and hormone-refractory prostate cancer cells." (PMID 26447757, 2015). "Finally, Golgi phosphoprotein 3 (GOLPH3), a protein involved in Golgi-membrane integrity and mTOR amplification, is enriched in prostate cancer patients urinary exosomes as well." (PMID 26196085, 2015). "Co-treatment of EBR with rapamycin, an upstream mTOR pathway inhibitor, prevented EBR-induced cell viability loss and PARP cleavage in LNCaP prostate cancer cells, suggesting that EBR could induce ER stress in these cells." (PMID 26353013, 2015). "Furthermore, activations of the AR, PI3K, mTOR, NFκB and Hedgehog (Hh) signaling pathways are involved in the fatal development of castration-resistant prostate cancer during androgen ablation therapy." (PMID 24913494, 2014). "While mTOR has been reported to associate with the IKK complex to stimulate NF-κB in prostate cancer cells, to our knowledge mTOR has not been demonstrated to be a driver of NF-κB activity in DLBCL." (PMID 24970801, 2014). "Since AR expression levels are low in hormone naive tumors, addition of an inhibitor of PI3K/mTOR to the standard ADT of advanced prostate cancer may therefore be beneficial to patients with PTEN deleted tumor." (PMID 24062990, 2013). "Additionally, we have detailed the rationale and evidence supporting the application of select molecularly targeted radiosensitizers such as HSP90 inhibitors, tyrosine kinase inhibitors, and mTOR inhibitors in the treatment of prostate cancer." (PMID 23863691, 2013).
prostate carcinoma (continued). "Also in a panel of multiple myeloma, glioblastoma, and prostate cancer cell lines, PTEN deficiency was reported to be associated with enhanced sensitivity to the allosteric mTOR inhibitor Temsirolimus (CCI-779)." (PMID 22970424, 2012). "Indeed, most patients with prostate cancer have at least one activated component of the mTOR signalling pathway." (PMID 22782340, 2012). "Although preclinical studies show mTOR inhibitors reverting prostatic neoplasia and reducing cell growth and proliferation, the clinical experience of mTOR inhibition in men with castrate-resistant prostate cancer has been disappointing." (PMID 22782340, 2012). "Inhibitors of the mammalian target of rapamycin (mTOR) might become a novel tool to treat advanced prostate cancer." (PMID 22782340, 2012). "A number of reports have also suggested targeting mTOR in prostate cancer." (PMID 22614157, 2012). "Although not surprising, this difference raises the commercially relevant hypothesis that a ‘second use’ for mTOR inhibitors could well be confirmed for not limited to, prostate cancer." (PMID 20011464, 2009). "Future studies directed at delineating mTOR activation may assist in revealing the mechanism(s) by which cyclin D1 accumulates in prostate cancer." (PMID 17375037, 2007). "Our mechanistic studies revealed that HSPB8 knockdown promoted phosphorylation of AKT and mTOR, which aligned with our speculation, i.e., the inhibitory role of HSPB8 in prostate cancer was, at least in part, linked to the inactivation of PI3K−AKT signaling pathway." (PMID 41190325, 2025). "Furthermore, we used rapamycin, an mTOR inhibitor, to determine whether the AMPK/mTOR signaling pathway regulates autophagy in prostate cancer cells." (PMID 40661871, 2025). "Moreover, the PI3K/AKT/mTOR signaling pathway plays a pivotal role in cell cycle regulation, growth, proliferation, and apoptosis, with its aberrant activation markedly contributing to endocrine therapy resistance in prostate cancer." (PMID 41079787, 2025). "We compared the impact of PI3K/AKT/mTOR pathway inhibitors with different selectivity profiles on in vitro cell proliferation and on caspase 3/7 activation as a marker for apoptosis induction, and observed the strongest effects in the androgen-sensitive prostate cancer cell lines VCaP and LNCaP." (PMID 38225213, 2024). "This can be explained in part by the very low number of prostate tissues for our Western blot analysis but could also reflect the contradictory role of p-mTOR/mTOR found in prostate cancer patients whose elevated levels positively correlated with a favorable prognosis." (PMID 38611022, 2024). "Additionally, ERG alterations may also have an impact on mTOR signaling pathway activation in primary prostate cancer and the development of castration-resistant disease." (PMID 39125671, 2024). "Notably, ChIP-sequencing studies revealed that mTOR directly engages with thousands of regulatory regions of Pol II-transcribed genes in both mouse liver and human prostate cancer cells, suggesting profound regulatory roles of mTOR across a plethora of transcriptional programs." (PMID 38727317, 2024). "Interestingly, the present study demonstrated that Piezo1 regulation of the cell cycle in prostate cancer cells is associated with the Akt/mTOR pathway, but not with the ERK1/2 pathway." (PMID 38690080, 2024). "Thus, mTOR activation induces the development of prostate cancer by inhibiting cellular apoptosis." (PMID 39349424, 2024).
prostate carcinoma (continued). "In addition, in prostate cancer cells, our data revealed that variations in phosphatidylserine exposure, membrane permeabilization, and cellular apoptosis were associated with differential IP3 receptor expression and PI3K/AKT/mTOR modulation." (PMID 37240163, 2023). "Therefore, baicalein may inhibit the occurrence and development of androgen-independent prostate cancer through the Cav1/AKT/mTOR pathway." (PMID 37910338, 2023). "Moreover, GNE-493 (250 nM)-induced death and apoptosis in primary prostate cancer cells were more potent than the same concentration of LY294002 (the pan PI3K-Akt-mTOR inhibitor) or INK-128 (the mTOR kinase inhibitor) in priCa-1 or priCa-2 primary cancer cells." (PMID 35296639, 2022). "Therefore, the Akt-mTOR-independent mechanisms could possibly participate in GNE-493-induced cytotoxicity in prostate cancer cells as well." (PMID 35296639, 2022). "Apart from a possible statistical bias related to the limited sample size of the study cohort, one explanation might be that mTOR activation in low-grade PeCa could accelerate translational activity and oxygen consumption as it was previously assumed for prostate cancer." (PMID 34066040, 2021). "In addition, S. nigrum could attenuate the malignant phenotype and tumor growth through the MAPK/mTOR signaling pathway in hepatocellular carcinoma and the p38 signaling pathway in prostate cancer cells." (PMID 33494738, 2021). "Indeed, the activation of the PI3K-Akt-mTOR pathway induced by PTEN loss and anti-AR treatments may promote prostate cancer cells proliferation and survival in androgen-reduced conditions." (PMID 35011901, 2021). "There are a number of on-going Phase I/II trials currently investigating dual-PI3K/mTOR inhibitors in combination with chemotherapy or targeted therapies in breast cancer, renal cell and prostate cancers with promising results that may prove useful for ovarian cancer trials in the future." (PMID 35582310, 2021). "Thus, the mTOR suppression in DU145 prostate cancer cells treated with SF5-SAHA might be a mechanism of this new compound preventing angiogenesis, too." (PMID 34959719, 2021). "Thus, our finding that the polyphenols attenuate SGK1 phosphorylation at Ser422, may suggest a role of the PI3K/mTOR pathway in the mechanism of the cytostatic effect of CUR + CA on prostate cancer cells." (PMID 34679726, 2021). "Indeed, testosterone binding to GPRC6A has been demonstrated to activate ERK, Akt and mammalian Target of Rapamycin (mTOR) signaling pathways in a time and dose-dependent manner, resulting in an increased cell proliferation and inhibition of autophagy in prostate cancer cells." (PMID 34831222, 2021). "Thus, the discovery of small molecules that can restore DEPTOR expression to inactivate mTOR/AKT signaling might be an attractive approach for future anti-prostate cancer therapy." (PMID 31685947, 2020). "Similarly, MK-2206 was shown to significantly reduce tumor growth in a PTEN-deficient prostate cancer model text, mTOR activity was not suppressed suggesting that mTOR signaling is regulated independently of AKT in this setting." (PMID 33105713, 2020). "Interestingly, in 2010 Dubrovska and colleagues showed how a combinatorial approach, based on conventional chemotherapy and NVP-BEZ235, a dual PI3K/mTOR inhibitor, leads to significant tumor regression targeting both bulk tumor cells and prostate cancer progenitors (PCPs), respectively." (PMID 31366089, 2019). "Radiation-induced activation of the PI3K/Akt/mTOR pathway may limit the effectiveness of radiotherapy and inhibition of this pro-survival pathway enhanced sensitivity to radiotherapy in glioblastoma and prostate cancer cells." (PMID 30774777, 2019).
prostate carcinoma (continued). "This capability has been shown in a variety of cells, including PC-3 and C4-2 cells, prostate cancer cells, and colorectal cancer cells, where CDDO-Me inhibits the growth and causes cells death at intermediate–high concentrations (0.625–2.5 μM) through the inhibition of NF-κB, p-Akt, and mTOR." (PMID 31766211, 2019). "This may exploit tumor-specific characteristics, such as targeting Vascular Endothelial Growth Factor (VEGF) signaling and mammalian Target of Rapamycin (mTOR) activity in renal cancer and inducing survival factor deprivation by targeting androgen signaling in prostate cancer." (PMID 29371637, 2018). "Western blot analysis indicated DT-13 significantly decreased the phosphorylation of PDK1, Akt, mTOR as well as p70S6K, suggesting the pro-apoptotic and anti-metastatic effects of DT-13 on prostate cancer cells might be attributed to the blockade of PI3K/Akt pathway." (PMID 30581390, 2018). "Furthermore, Sal decreases phosphorylated of AKT and phosphorylated mTOR in prostate cancer cells." (PMID 29433536, 2018). "Thus, the promotion of autophagy by mTOR inhibition may improve radiotherapy efficacy in prostate cancer." (PMID 28320471, 2017). "Our recent work confirmed that PC-1/PrLZ interacts with 4E-BP1, a downstream factor of mTOR, and mains its protein stability via blocking ubiquitin-mediated proteasome degradation, through which PC-1/PrLZ inhibits autophagy and contributes to chemoresistance of prostate cancer cells." (PMID 27694690, 2016). "Therefore, treatment with MELK inhibitor could be a desirable anticancer strategy for tumors with enhanced activity in the PI3K/Akt/mTOR pathway, such as breast, lung, ovarian, and prostate cancers." (PMID 26871945, 2016). "Finally, we returned to our mouse prostate cancer model and determined whether Sag deletion will indeed block the activation of the PI3K/AKT/mTOR signal triggered by Pten loss." (PMID 27955654, 2016). "Interestingly, it has been reported that HIF-1α may in turn stimulate mTOR signaling in prostate cancer stem cells leading to their resistance to selective mTOR inhibitors." (PMID 27821815, 2016). "Additionally, we observe activation of AKT and mTOR that may in part explain growth inhibition of invasive prostate cancer cells in hypoxic condition." (PMID 24515947, 2014). "Interestingly, GDC-0980 treatment alone decreased AR levels and this effect could be enhanced further by the addition of CDX, suggesting that mTOR activity may contribute to elevated AR protein levels, similar to the signaling observed in prostate cancer." (PMID 25103565, 2014). "Furthermore, REDD1 induction by MSeA is independent of AKT and the mTOR inhibition in prostate cancer cells causes partial resistance to MSeA-induced growth reduction in hypoxia." (PMID 24515947, 2014). "Furthermore, testosterone regulates mTOR activity in prostate cancer cells." (PMID 21812961, 2011). "Phosphatase and tensin homolog (PTEN) is often deregulated in advanced prostate cancers, leading to the activation of the PI3K-Akt-mTOR pathway and increased cell survival." (PMID 41216191, 2025). "Our investigation uncovered the suppression of mTOR activity and Rheb expression after SMC4 knockdown, suggesting the potential role of SMC4 in governing the growth and metastasis of prostate cancer cells through the Rheb/mTOR signaling pathway." (PMID 40278414, 2025).